TOP1 (DNA topoisomerase I)
Diseases named in the same sentence as TOP1 in open-access papers (continued):
Sharing a sentence is not in itself a finding about the gene and the disease.
cancer (continued). "Camptothecin is the third most in-demand alkaloid after taxol and vinca-alkaloids for anti-cancer applications, and inhibits DNA topoisomerase I in cancer cells leading to cell death." (PMID 33446714, 2021). "Although both Trop-2 and TOP1 expression have been well-documented in various cancers including breast cancer, predictive testing was not conducted in this trial (IMMU-132-01 (NCT 01631552) clinical trial." (PMID 32530388, 2021). "TOP1 plays an important role in the rRNA genes, and TOP1 inhibitors such as topotecan are used in cancer therapy though their clinical use has been limited due to hematological toxicity." (PMID 34440328, 2021). "Inhibitors of topoisomerase I (Top1) that result in stalled Top1 cleavage complexes (Top1cc) are commonly employed against carcinoma." (PMID 34568317, 2021). "Protein kinase CKII previously played a key role in phosphorylation and regulation of TOP1 in a large number of cancer cell lines." (PMID 32423158, 2020). "In some cancer cells, p14ARF has also been observed to interact with and regulate the activity of TOP1." (PMID 32423158, 2020). "The inhibition of Top1 by the G4 oligos was correlated with the inhibition of DNA replication, and this antiproliferative effect was specific to cancer cells." (PMID 32059547, 2020). "Multiple recent studies suggest that G4 DNA-forming oligos can preferentially bind and interfere with the activity of Top1, which has been a very important target of anti-cancer therapy." (PMID 32059547, 2020). "Derived from elesclomol (in clinical trials: phase 3 against melanoma and randomized phases 2 and 3 for the treatment of a variety of other cancers), the elesclomol-Cu(II) complex 13 inhibits Top1 and induces apoptosis in cancer cells." (PMID 33027952, 2020). "Actually, it should be noted that growing evidence has revealed that CPT and CPT analogs can also have Top1-independent activity to inhibit cancer cells or neutralize HIV-1." (PMID 33217967, 2020). "Concomitant with the increased availability of 5-FU and FP drugs were increased investigations into mechanisms beyond TS inhibition that are important for the anti-cancer activities of FP drugs, which include the poisoning of DNA topoisomerase 1 (Top1;)." (PMID 32751071, 2020). "Other studies have demonstrated that Top1 catalytic mutants, which harbor reduced duplex DNA cleavage abilities, exist in cancer cell lines and cancer patients." (PMID 32059547, 2020). "For instance, digoxin and proscillardin A inhibits DNA topoisomerase I whereas bufalin and digoxin inhibit DNA topoisomerase II as well to induce cell death in cancer cells." (PMID 32784680, 2020). "While both Top1 mutations and secondary genomic rearrangements have been discovered in cancer patients treated with CPT or CPT derivatives, a link between these documented Top1 mutations and G4-induced secondary genomic rearrangements has not been studied." (PMID 32059547, 2020). "First, consistent with the cell culture experiments demonstrating that the reduced levels of Top1 confer resistance to CPT, cancers relapsing after chemotherapy spontaneously become resistant to CPT through reduced expression of Top1." (PMID 32059547, 2020). "This is in contrast to the reported finding that reduced Top1 expression and/or Top1 catalytic activity in cancer cells is associated with increased resistance to CPTs and that the increased Top1 expression in cancer cells sensitizes CPTs." (PMID 33217967, 2020). "Both nuclear Top1 and Top2 are important targets for cancer chemotherapy, and Top inhibitors are used in therapeutic protocols." (PMID 33027952, 2020). "Dual targeting of TS/Top1 by DNA-directed fluoropyrimidines such as F10 shows promising activity in pre-clinical cancer models." (PMID 31930190, 2019). "DNA Topoisomerase I (Top1) represents an attractive target for cancer chemotherapy, as this enzyme plays a crucial role in the DNA replication process by relaxing the nucleic acid’s supercoiled structure." (PMID 30781470, 2019).
cancer (continued). "Top1 is over-expressed in several human neoplasms except normal tissues, so it can be presumed that the rapidly proliferating cancer cells are more closely related to Top1 than the healthy cells." (PMID 31167344, 2019). "This is consistent with our findings that FL118 inhibition of cancer cell growth occurs at the high pM to low nM range; whereas its effects on Top1 activity require μM levels." (PMID 31439015, 2019). "Topoisomerases are well-validated targets for cancer chemotherapy and DNA topoisomerase 1 (Top1) is the sole target of the camptothecin (CPT) class of anticancer drugs." (PMID 31930190, 2019). "A major advance for targeting DNA for cancer treatment was the discovery that camptothecin (CPT), a natural product identified by Wall and Wani in a screen for natural products with anti-cancer activity, targeted DNA topoisomerase 1 (Top1)." (PMID 31930190, 2019). "At the same time, structure-based and computer-aided drug design have made enormous efforts with the publication of Top1 crystal structures to the discovery, design and development of anti-cancer candidates targeting Top1." (PMID 31167344, 2019). "The clinical implications for cancer patients treated with TOP1 inhibitors and for patients suffering from exaggerated cytokine production are discussed." (PMID 31242600, 2019). "CPT is a chemotherapeutic agent that exhibits anti-cancer activity due to its inhibition of DNA topoisomerase I, inducing DNA damage and DSB formation." (PMID 31803609, 2019). "Ir is a water-soluble anti-cancer derivative of camptothecin, which can induce the apoptosis of cancer cells by inhibiting DNA topoisomerase I. Owing to its amphiphilic structure, Ir-ss-Qu conjugate can self-assemble into NPs (Ir-ss-Qu NPs) in water." (PMID 31534517, 2019). "We present an overview of this evolving literature, which has implications for how targeting of Top1 with nucleoside analogs can be used more effectively for cancer treatment." (PMID 31930190, 2019). "Consistent with a role for this pathway in cellular recovery from TOP1cc-induced damage, inhibition of CHK1179–181 or ATR182,183 sensitizes cancer cells to TOP1 poisonsin vitro and in xenografts." (PMID 31602296, 2019). "In conclusion, our results uncover that the well-studied anti-cancer TOP1 poison CPT can overcome KMT1A-mediated repression of MyoD activity and induce a differentiated myogenic phenotype in aRMS cells." (PMID 29899822, 2018). "On the other hand, topotecan is semi-synthetic derivative of camptothecin and acts as an inhibitor of DNA topoisomerase I. Inhibition of DNA topoisomerase I results in inhibition of DNA replication and transcription that eventually leads to cancer cell death." (PMID 30257426, 2018). "TDP1 plays an essential role in the resistance of cancer cells to currently used antitumour drugs based on Top1 inhibitors such as topotecan and irinotecan." (PMID 30191738, 2018). "AgNPs are known to exhibit anticancer activity and DNA-topoisomerase I inhibitor such as CPT analogs exhibit toxic effects against cancer cells by inducing the activation of apoptotic caspases and formation of ROS and ultimately increases anticancer activity." (PMID 30647812, 2018). "A renowned case of enzymatic DPC forms following exposure of Topoisomerase 1 to Topoisomerase 1-specific poisons called camptothecins (namely Top1 cleavage complex, or Top1-cc), which are widely used in cancer therapy for their cytotoxicity." (PMID 30170832, 2018). "A robust correlation between TOP1 CN status, gene expression level, protein expression level and -activity in cancer cell lines and cancer tissues has been reported." (PMID 28077117, 2017). "The (TOP1) gene is located on chromosome 20 at 20q12 and this region frequently undergoes CN alterations in various cancers." (PMID 28077117, 2017). "The plausible link between tumor tissue levels of Top1 and effect of Top1 inhibitors in cancer treatment has been investigated by different methods." (PMID 28077117, 2017).
cancer (continued). "While the accumulation of TOP1cc on DNA can lead to cell death, paradoxically, it is this toxic effect that makes the TOP1 activity a prime target for cancer therapy since ancient times." (PMID 27181710, 2016). "Increased TOP1 CN, Top1 mRNA or protein expression or enzyme activity has been correlated to cancer cells’ sensitivity to Top1 targeting drugs." (PMID 26801902, 2016). "This suggests that LMP400 can remain active in cancers resistant to SN-38, which display upregulation of this multidrug resistance protein, if TOP1 is wild-type." (PMID 27029323, 2016). "This has been proven in many tumor models including NSCLC cancer using DNA topoisomerase 1 (Top1) poisons such as camptothecin (CPT)." (PMID 25742788, 2015). "Given that they are highly expressed in aggressive cancer cells and are essential to cancer cell survival, top1 and top2α are potential drug targets for treating human malignancies." (PMID 26462155, 2015). "So far, only CPT derivatives such as topotecan and irinotecan have been approved by the FDA as Top1-targeted drugs for various forms of cancer." (PMID 25460368, 2014). "Inhibition of TDP1 is therefore an attractive strategy for targeting cancer cells in conjunction with TOP1 poisons." (PMID 24637157, 2014). "Several anticancer drugs drive cancer cells toward apoptosis by inducing the Top1-DNA cleavage complex (Top1-DNAcc)." (PMID 25460368, 2014). "We describe here our strategy of biomarker-guided repurposing of chemotherapeutic drugs for cancer therapy, exemplified with the repurposing of Top1 inhibitors and Top1 as a potential predictive biomarker." (PMID 24400218, 2013). "Taken together, the TOP1 locus appears to undergo frequent copy number increases in several cancer types." (PMID 24400218, 2013). "The anti-cancer drug camptothecin inhibits replication and transcription by trapping DNA topoisomerase I (Top1) covalently to DNA in a “cleavable complex”." (PMID 24194914, 2013). "One class of anti-cancer drugs of particular interest to us is that of Top1 inhibitors, in particular irinotecan." (PMID 24400218, 2013). "Subsequent studies have largely confirmed these data finding 2- to 40-fold increases of TOP1 mRNA, Top1 protein, or activity in cancer tissue." (PMID 24400218, 2013). "This review describes our strategy of biomarker-guided repurposing of chemotherapeutic drugs for cancer therapy, taking the repurposing of topoisomerase I (Top1) inhibitors and Top1 as a potential predictive biomarker as case in point." (PMID 24400218, 2013). "The DNA topoisomerase I (TOP-I) is considered as one of the most effective targets for developing anti-cancer agents, not only due to its abnormally high intracellular levels, but also by the restriction of corrective mechanisms’ cleavage of stabled TOP-I-DNA." (PMID 22580401, 2012). "Representative drugs from several major cancer drug classes (alkylating agents, platinum compounds, DNA topoisomerase I and II inhibitors, antimetabolites, and mitotic spindle poisons) were chosen." (PMID 27605335, 2012). "DNA topoisomerase I (Top1) is over-expressed in tumour cells and is an important target in cancer chemotherapy." (PMID 21966440, 2011). "Camptothecin stabilizes Top1/dsDNA covalent complexes which ultimately results in cell death, and this makes Top1 an anti-cancer target." (PMID 21912628, 2011). "CPT kills cancer cells by interfering with the function of DNA topoisomerase I (TopI) during DNA replication in the S-phase." (PMID 20423495, 2010). "We are planning retrospective studies on DNA samples from cancer patients who have been treated, for instance, with combinations of antifolates (such as raltitrexed) and Top1 inhibitors (such as irinotecan) in order to validate our observations." (PMID 16983402, 2006).
cancer (continued). "While an effect on 3’UTR isoform expression was not tested in that study, BRD4 is known to interact with and recruit the cleavage and polyadenylation machinery during transcription elongation and co-inhibition of BRD4 and TOP1 induces readthrough transcription with implications for other cancers." (PMID 40654921, 2025). "Therefore, TDP2 inhibition combined with a TOP1 inhibitor and radiomimetic drugs results in cancer cell sensitization." (PMID 40155951, 2025). "Finally, the yeast model system enabled us to show that Top1 mutants identified in human cancer cells have detrimental and pathological functions beyond conferring resistance to CPT and CPT analogs." (PMID 41009588, 2025). "Additionally, luteolin-7-O-glucoside, the major flavonoid in this plant, inhibits various human cancer cell lines by acting as a potent DNA topoisomerase I poison." (PMID 40366497, 2025). "Top1 is an essential cellular enzyme and historically important target of anti-cancer drugs." (PMID 41009588, 2025). "Cancer cell sensitivity to TOP1cc trapping agents is thought to result from a combination of TOP1cc accumulation and replication stress triggered by unresolved TOP1:DNA adducts." (PMID 40796804, 2025). "However, further mechanistic studies are required to clarify how variations in TOP1 levels influence DoG RNA synthesis in human cancers." (PMID 41155268, 2025). "This superior performance highlights the potential of our approach in accelerating the discovery and optimization of novel, potent ADC payloads, particularly those targeting DNA Topoisomerase I, potentially leading to more effective and targeted cancer therapies." (PMID 40430004, 2025). "In addition, agarose gel electrophoresis and molecular docking studies indicated that compound 42 exhibits potent inhibition of Top1, leading to G2 cell cycle arrest and trigger cancer cell apoptosis." (PMID 40141117, 2025). "It is worth noting that we have found that specific genes, such as CD71 and TOP1, play an indispensable role in gynecological tumor cell lines and may be key factors driving cancer development." (PMID 40046734, 2025). "DNA topoisomerase I (Topo I) is a well-established target for cancer treatment, and many studies have shown that different cancer cell genes could be targeted more selectively with one type of Topo I inhibitor." (PMID 40005202, 2025). "TOP1 is a protein involved in DNA replication, crucial for preventing DNA damage, and has recently emerged as a potential target for anticancer chemotherapy in cancer research." (PMID 38711645, 2024). "However, additional mechanistic insight is needed to fully understand how differential TOP1 levels are related to changes in DoG RNA production in human cancers." (PMID 38959318, 2024). "UDCA enhanced DNA topoisomerase I inhibitor-induced apoptosis in several cancer cell lines." (PMID 38782891, 2024). "Hence, new strategies are needed to improve drug delivery efficiency to enhance DNA topoisomerase I inhibition and DNA damage and elicit a vigorous anticancer cancer immunity response." (PMID 38571953, 2024). "This suggests that TOP1 inhibitor may contribute the release of tumor antigen, thereby increasing cancer immunogenicity and augmenting the efficacy of immunotherapy." (PMID 38564022, 2024). "The DNA damage repair (DDR) protein topoisomerase I (TOP1) has been linked to various cancers, yet its distinct roles and mechanisms in CC are not fully elucidated." (PMID 39156107, 2024). "TOP1 is overexpressed in several types of cancer cells, including GC." (PMID 38783957, 2024). "This anti-cancer effect could be mediated by decreasing the activity of DNA topoisomerase I and II in eukaryotes." (PMID 39598770, 2024). "DNA topoisomerase I can contribute to cancer genome instability." (PMID 38787953, 2024). "Our findings revealed that TOP1 regulates numerous genes with pro-cancer inflammatory features." (PMID 39156107, 2024).
cancer (continued). "Currently, nearly 50% of clinical cancer treatments rely on the use of one or more TOP1 inhibitors." (PMID 38783957, 2024). "In addition, cancer cells require rapid proliferation to dominate in competing with normal cells for fuels, and DNA topoisomerase 1 (TOP1) plays a crucial role in making it." (PMID 39062453, 2024). "Interestingly, compound 77 exhibited negligible cytotoxicity (CC50 > 100 μM) when tested against human cancer cells; however, it significantly enhanced the cytotoxic activity of the Top1 inhibitor—camptothecin—in cancer cells." (PMID 38139858, 2023). "For example, Liu's group combined CPT and a well-investigated porphyrin derivative, chlorin e6 (Ce6), to eradicate human cervical carcinoma when Ce6 was activated to produce ROS to kill cancers and CPT caused DNA topoisomerase-I inhibition and cell death in PDT-resistant cancer cells." (PMID 37497002, 2023). "The repercussions of this for TOP1 poison-based cancer therapy remains to be revealed." (PMID 37945566, 2023). "It has been reported that TOP1 inhibitors can provide strong tools to restrain DNA replication and could be helpful for establishing new strategies for efficient cancer treatments." (PMID 37587470, 2023). "Hence, TOP1 inhibitors are of particular interest as potential anti-parasitic drugs, while TOP1 poisons are of high interest as potential anti-cancer agents, since they convert TOP1 activity into a cell killer." (PMID 37242440, 2023). "Upon treatment of cancer cells, SN-38 binds to Top1 and stabilizes Top1-DNA complexes." (PMID 37108395, 2023). "In short, ssDNA damage response mediated by ATR/Chk1 may govern the sensitivity of cancer cells to TOP1 inhibitors." (PMID 35844787, 2022). "As LMP776 and CPT induced similar micronuclei levels in HeLa and SCLC cancer cell lines, we next tested whether the studied TOP1 poisons could also activate immune gene expression in H209, H889 and DMS114 cells (human SCLC lines)." (PMID 35794238, 2022). "Thus, this type of compound is a promising platform for further development of drugs for the accompanying cancer therapy in combination with Top1 inhibitors." (PMID 36615517, 2022). "Next, as TOP1 poisons were able to increase micronuclei in cancer cells, we asked whether the cGAS/STING signalling cascade was activated by micronuclei leading to innate immune gene expression, as previously reported in SV40 expressing cells and cancer cells." (PMID 35794238, 2022). "Therefore, immunomodulatory effects of Top1 poisons likely depend on patient-specific molecular features of human cancers." (PMID 35794238, 2022). "Its approval helps bring the TOP1 inhibitor back to the forefront as an anti-cancer drug." (PMID 35844787, 2022). "Thus, targeting TDP1 is expected to result in minimal toxicity but has the potential to selectively sensitize cancer cells over normal cells to TOP1 poisons." (PMID 35869071, 2022). "Importantly, the essential role of PARylation in regulating TOP1-DPC repair is highlighted by the synergistic effect of combining PARP inhibitors and TOP1 poisons to kill cancer cells." (PMID 35860355, 2022). "Overall, our results suggest that the expression of Top1 mutants could induce additional genome rearrangements in cancer cells by supporting G4-formation and -stabilization." (PMID 35291312, 2022). "Interestingly, TOP1 poisons at relatively low doses have been shown to elicit other delayed effects relevant to immunological responses in several cancer models." (PMID 35794238, 2022). "Since WRN‐depleted cancer cells or WS patient‐derived cells are highly sensitive to TOP1 inhibitors, we envisaged that WRN might be orchestrating TOP1cc removal and subsequent NF‐κB activation to offer therapeutic resistance in WRN‐proficient cells." (PMID 35582959, 2022). "JNK activation-mediated constitutive elevation of MYC expression may represent a novel mechanism governing cancer cell sensitivity to TOP1-targeting therapy." (PMID 35844787, 2022).